Y_RNA (Y RNA )
Gene: Miscellaneous RNA gene on chromosome 5 (128,371,099 to 128,371,212, reverse strand). Ensembl gene ENSG00000207290.
Homologues: Orthologues: chimpanzee Y_RNA (98% identical), macaque Y_RNA (93% identical), pig Y_RNA (71% identical). Paralogues in human: Y_RNA (81% identical), Y_RNA (78% identical), RNY1P5 (77% identical), Y_RNA (77% identical), Y_RNA (76% identical), RNY1 (75% identical), RNY1P1 (75% identical), Y_RNA (75% identical), RNY1P6 (74% identical), Y_RNA (74% identical), Y_RNA (73% identical), Y_RNA (72% identical), and 90 more.